SNHG3 (small nucleolar RNA host gene 3)
Diseases named in the same sentence as SNHG3 in open-access papers (continued):
Sharing a sentence is not in itself a finding about the gene and the disease.
bladder cancer (16 papers, 2020 to 2025). "Elevated SNHG3 expression was positively linked to the TNM stage along with the histological grade of individuals with bladder cancer." (PMID 33859998, 2021). "Even though our research uncovered the mechanism by which lncRNA SNHG3 functions as an up‐regulator in bladder cancer, there are unlimited feasibilities underlying." (PMID 32596993, 2020). "High SNHG3 expression is associated with larger tumors in various cancers, such as bladder cancer." (PMID 41042421, 2025). "In addition, upregulated SNHG3 expression was shown to result in the dismal prognosis of bladder cancer patients, causing lower OS and DFS." (PMID 33859998, 2021). "In summary, our study indicated that lncRNA SNHG3 may serve as a novel diagnostic or therapeutic target of bladder cancer." (PMID 32596993, 2020). "Moreover, elevated SNHG3 content was strongly linked to the TNM stage along with histological grade of individuals with bladder cancer, but irrelevant to other clinical features, including gender, lymph node metastasis, age, distant metastasis, as well as tumor size." (PMID 33859998, 2021). "Therefore, our study indicated that lncRNA SNHG3 may serve as a novel diagnostic and therapeutic target of bladder cancer." (PMID 32596993, 2020). "Therefore, research shows that lncRNA SNHG3 may become a new diagnostic and treatment target for bladder cancer." (PMID 33292213, 2020). "In vitro experiments show that reducing SNHG3 expression weakens bladder cancer cells’ ability to promote tube formation, while increasing SNHG3 promotes angiogenesis." (PMID 41042421, 2025). "In bladder cancer, SNHG3 regulates c-MYC to stabilize BMI1 mRNA, highlighting its role in tumorigenesis and proposing the SNHG3/c-MYC/BMI1 axis as a novel therapeutic target." (PMID 39349640, 2024). "SNHG3 is a member of a lncRNA family that plays a leading role in a variety of cancers, including liver, colorectal, and bladder cancers." (PMID 35528235, 2022). "Altogether, these data revealed that SNHG3 silencing repressed migration along with the infiltration of bladder cancer cells." (PMID 33859998, 2021). "Herein, the data revealed lncRNA SNHG3 upregulation in bladder cancer tissues, as well as cell lines in contrast with the matched bladder non-malignant tissues and SV-HUC1 cells, respectively." (PMID 33859998, 2021). "Lastly, we established that SNHG3 was highly expressed in the bladder cancer cells (5637 and SW780) in contrast to that in SV-HUC1, implying that SNHG3 is a bladder cancer oncogene." (PMID 33859998, 2021). "In our research, we first reported that lncRNA SNHG3 was up‐regulated in bladder cancer tissues and positively related to poor clinical prognosis." (PMID 32596993, 2020). "In bladder cancer cells, decreased SNHG3 downregulates expression of MYC genes." (PMID 41042421, 2025). "The lncRNA SNHG3 promotes the progression of bladder cancer via the miR-515-5p/GINS2 axis." (PMID 34101736, 2021). "Collectively, the data confirmed that suppression of SNHG3 inhibited bladder cancer cell growth." (PMID 33859998, 2021). "In conclusion, our study identified that lncRNA SNHG3 acted as an oncogene in bladder cancer." (PMID 32596993, 2020). "Additionally, knockdown of miR‐515‐5p reversed the inhibited tumorigenesis of bladder cancer cells induced by silencing SNHG3." (PMID 32596993, 2020). "Knockout of SNHG3 expression using CRISPR-Cas9 has been shown to suppress proliferation, migration, invasion, and angiogenesis in bladder cancer cells in vitro." (PMID 41042421, 2025). "The lncRNA small nucleolar RNA host gene 3 (SNHG3) further exemplifies this complexity, promoting bladder cancer proliferation and metastasis through the miR-515–5p/GINS2 axis." (PMID 38249783, 2024). "For example, the expression of lncRNAs such as TUC338 and PVT1 can be used as biomarkers for early diagnosis of bladder cancer, while the expression of PCAT6, NRON, GAS6-AS2, SNHG3, lncRNA TP73-AS1, and LINC00641 can predict poor prognosis of bladder cancer." (PMID 37592177, 2023).
bladder cancer (continued). "Further functional assays illustrated that SNHG3 silencing, by CRISPR-dCas9, repressed the bladder cancer cell growth, as well as migration and enhanced cell apoptosis." (PMID 33859998, 2021). "Moreover, the OS and DFS in the SNHG3 overexpression group was remarkably lower in contrast to that in the SNHG3 down-regulation group, indicating that SNHG3 could be applied as a prognostic indicator for bladder cancer." (PMID 33859998, 2021). "However, the role of lncRNA SNHG3 in bladder cancer remains unknown." (PMID 32596993, 2020). "Further investigation showed that SNHG3 significantly enhanced the proliferation, invasion, migration, and EMT of bladder cancer cells in vitro and in vivo through the regulation of GINS complex subunit 2 (GINS2), a member of the GINS complex involved in DNA replication, by “sponging” miR-515–5p." (PMID 36605618, 2023). "At the same time, SNHG3/miR-2682-5p/HOXB8 axis, ELK1/lncRNA-SNHG7/miR-2682-5p feedback loop, and LINC01006/miR- 2682-5p/HOXB8 axis can promote the proliferation and migration of oral squamous cell carcinoma, bladder cancer, and pancreatic cancer, respectively." (PMID 35465266, 2022). "In contrast with the matching non-malignant bladder peritumoral tissues, SNHG3 expression was highly expressed in 68.3% (28 of 41) of bladder cancer tissues." (PMID 33859998, 2021). "Moreover, the down‐regulation of lncRNA SNHG3 significantly inhibited the tumorigenesis and epithelial‐mesenchymal transition (EMT) process of bladder cancer cells in vitro and vivo." (PMID 32596993, 2020). "According to the promoter sequence of SNHG3, we designed three different sgRNAs (sg-SNHG3-3, sg-SNHG3-2, as well as sg-SNHG3-1) targeting SNHG3 and evaluated their efficiencies in 5637 and SW780 bladder cancer cells inserted with a sg-SNHG3 or sgRNA negative control (sg-NC)." (PMID 33859998, 2021).
glioma (15 papers, 2019 to 2025). A benign or malignant brain and spinal cord tumor that arises from glial cells (astrocytes, oligodendrocytes, ependymal cells). "Significantly decreased levels of LINC00205, FGD5-AS1, and SNHG7 were characteristic for high-grade gliomas as compared to lower-grade tumours, while SNHG3 showed opposite associations." (PMID 36597408, 2023). "In addition, sufficiency of SNHG3 reduced miR-384, whereas deficiency of SNHG3 elevated miR-384 expression in glioma cells." (PMID 33817254, 2020). "Moreover, rescue experiments implicated that restoration of HDGF abrogated SNHG3 silencing induced suppressive effect on glioma cell proliferation." (PMID 33817254, 2020). "Research demonstrated SNHG3's role in glioma by promoting tumorigenesis through miR-485-5p sequestration, leading to increased LMX1B expression and facilitating glioma cell proliferation, migration, and invasion." (PMID 39349640, 2024). "In our study, we attempted to illuminate the biological mechanism of SNHG3 on glioma tumorigenesis, proliferation, migration, invasion, and apoptosis processes." (PMID 33817254, 2020). "We discovered that SNHG3 acts as an oncogene in glioma to promote cell progression by upregulating HDGF expression through interaction with miR-384." (PMID 33817254, 2020). "Consistently, SNHG3 expression was upregulated dramatically in glioma cell lines A172 and SHG44 in comparison with human astrocyte cell line NHA." (PMID 33817254, 2020). "The expression of SNHG3 in 42 pairs of glioma tumors and normal tissues was determined using qRT-PCR to elucidate the role of SNHG3 in glioma development." (PMID 33817254, 2020). "For instance, SNHG3 enhances the malignant behaviors of glioma through silencing Kruppel-like factor 2 (KLF2) and p21 protein (p21) via recruiting EZH2 to the promoter of KLF2 and p21." (PMID 33292213, 2020). "Noticeably, high level of SNHG3 resulted in low survival rate, whereas low level of SNHG3 resulted in high survival rate within 60 days in glioma patients." (PMID 33817254, 2020). "Meanwhile, restoration of HDGF abrogated the inhibition of SNHG3 silencing on glioma cell progression." (PMID 33817254, 2020). "In conclusion, we clarified the regulatory effect of SNHG3/miR-384/HDGF axis on glioma cell proliferation, migration, invasion, and apoptosis." (PMID 33817254, 2020). "Identification of the function of SNHG3 in glioma cell progression was evaluated by CCK8, flow cytometry, and transwell assay." (PMID 33817254, 2020). "For instance, the upregulation of DANCR promotes glioma progression via Wnt signaling 18, and SNHG3 promotes glioma development by suppressing the expression of KLF2 and p21 expression." (PMID 32913464, 2020). "These experiments revealed that SNHG3 accelerates the malignancy of glioma by inhibiting transcription of KLF2 and p21." (PMID 33292213, 2020). "Generally, it is believed that SNHG3 may be an oncogene in glioma and may serve as a potential prognostic biomarker and therapeutic target for glioma." (PMID 33292213, 2020). "Likewise, SNHG3 served as an oncogene to enhance glioma malignant progression by KLF2 and p21 silencing." (PMID 33817254, 2020). "Collectively, we suggested that SNHG3 plays an oncogenic role in glioma." (PMID 33817254, 2020). "Altogether, SNHG3 promotes glioma cell development by regulating HDGF." (PMID 33817254, 2020). "Therefore, it is of great significance to illuminate the role of SNHG3 in glioma." (PMID 33817254, 2020). "Interestingly, HDGF rescued SNHG3 silencing mediated promotion on apoptosis in glioma." (PMID 33817254, 2020). "However, the regulatory effect of SNHG3 on glioma progression is still controversial." (PMID 33817254, 2020). "Furthermore, upregulated SNHG3 suggests a poor prognosis in patients with glioma." (PMID 33292213, 2020). "The expression of SNHG3 and HDGF was upregulated, whereas miR-384 was downregulated in glioma tissues, compared with the normal tissues." (PMID 33817254, 2020).
glioma (continued). "Moreover, SNHG3 or HDGF knockdown significantly suppressed proliferation, migration, and invasion and induced apoptosis in glioma." (PMID 33817254, 2020). "Essentially, miR-384 inhibitor abolished the suppression of SNHG3 silencing on HDGF mRNA and protein expression, validating that SNHG3 accelerates cell progression and induces apoptosis by upregulating HDGF expression via sponging miR-384 in glioma." (PMID 33817254, 2020). "In addition, SNHG3 or HDGF knockdown significantly attenuated glioma cell progression; however, restoration of HDGF expression remarkably enhanced proliferation, migration, and invasion in glioma." (PMID 33817254, 2020).
prostate carcinoma (14 papers, 2020 to 2025). A carcinoma that arises from epithelial cells of the prostate gland. "In the context of bone metastases, Small nucleolar RNA host gene 3 (SNHG3), a long non-coding RNA associated with snoRNA clusters, has been shown to enhance bone metastasis in prostate cancer." (PMID 40872531, 2025). "In prostate cancer, SNHG3 might serve as a diagnostic biomarker, as its expression levels can successfully differentiate prostate cancer tissues from normal prostate tissues based on the TCGA-PRAD database (area under the curve (AUC) = 0.917, 95% confidence interval [CI]: 0.867–0.966)." (PMID 41042421, 2025). "In prostate cancer cells, decreasing SNHG3 expression reduced the number of cells in the S phase, while increasing SNHG3 expression accelerated cell cycle transition from the G0/G1 phase to the S phase." (PMID 41042421, 2025). "SNHG3 exhibits high expression in prostate cancer cell lines and promotes various oncogenic processes while inhibiting apoptosis." (PMID 39349640, 2024). "SNHG3 was observed to modulate prostate cancer cell behaviors, such as migration, invasion, and epithelial-mesenchymal transition (EMT)." (PMID 39349640, 2024). "Functional assays revealed that SNHG3 overexpression promoted proliferation, migration, and invasion of prostate cancer cells while inhibiting apoptosis." (PMID 39606232, 2024). "We found that SNHG3 was aberrantly up‐regulated in prostate cancer cells than in human normal prostate epithelial cells." (PMID 32248648, 2020). "In our study, we firstly detected the expression of SNHG3 in prostate cancer cells using qRT‐PCR assay." (PMID 32248648, 2020). "In our study, we detected the subcellular location of SNHG3 and the results revealed that SNHG3 was mainly located on the cytoplasm of prostate cancer cells." (PMID 32248648, 2020). "We found SNHG3 was significantly highly expressed in prostate cancer cells, especially in PC3 and DU145 cells (*P < .05, **P < .01)." (PMID 32248648, 2020). "It is for the first time that the ceRNA axis of SNHG3/miR‐577/SMURF1 was uncovered in prostate cancer cells." (PMID 32248648, 2020). "Next, the oncogenic role of SNHG3 in prostate cancer was verified through in‐vitro and in‐vivo assays." (PMID 32248648, 2020). "SNHG3 knockdown inhibits prostate cancer cell proliferation, migration, and EMT processes, promoting cell growth." (PMID 33292213, 2020). "Moreover, a comparison between metastatic prostate cancer tissues obtained from bone (B-PC, n = 21) and primary prostate cancer tissues (P-PC, n = 60) showed increased SNHG3 expression in B-PC samples." (PMID 41042421, 2025). "A study investigated the role of SNHG3 in prostate cancer (PCa)." (PMID 39349640, 2024). "Targeting SNHG3 may help to prevent prostate cancer metastasis as well as the treatment of metastatic prostate cancer, for which research experiments are currently underway." (PMID 39655078, 2024). "Moreover, SNHG3 has been found to promote tumorigenesis in vivo, suggesting its potential as a biomarker for diagnosing and treating prostate cancer." (PMID 39349640, 2024). "Therefore, in prostate cancer cells, SNHG3 can be considered a prognostic biomarker and a promising target against bone metastases." (PMID 37143733, 2023). "We then sought to search for the ceRNA axis with the involvement of SNHG3 in prostate cancer cells." (PMID 32248648, 2020). "In conclusion, SNHG3/miR‐577/SMURF1 axis was found in prostate cancer cells." (PMID 32248648, 2020). "In our study, we scrutinized the role and mechanism of SNHG3 in prostate cancer." (PMID 32248648, 2020). "SNHG3/miR‐577/SMURF1 axis was found in prostate cancer cells." (PMID 32248648, 2020). "In this work, SNHG3 exerted high expression in prostate cancer cell lines." (PMID 32248648, 2020). "Inhibited SNHG3 could suppress the progression of prostate cancer cells." (PMID 32248648, 2020). "MiR‐577 could bind to SNHG3 and regulate the progression of prostate cancer." (PMID 32248648, 2020).
prostate carcinoma (continued). "In conclusion, miR‐577 could bind to SNHG3 and regulate the progression of prostate cancer." (PMID 32248648, 2020). "In conclusion, inhibited SNHG3 could suppress the progression of prostate cancer cells." (PMID 32248648, 2020). "In conclusion, SNHG3/miR‐577/SMURF1 axis could modulate the progression of prostate cancer cells." (PMID 32248648, 2020). "SNHG3/miR‐577/SMURF1 axis could modulate the progression of prostate cancer cells." (PMID 32248648, 2020). "Multivariate Cox regression analysis revealed that elevated SNHG3 expression could serve as an independent predictor of mortality (hazard ratio [HR] = 1.752, 95% CI: 1.164–2.657, p = 0.008) and disease progression (HR = 7.598, 95% CI: 0.944–61.152, p = 0.037) in prostate cancer." (PMID 41042421, 2025). "Based on validation from the GEPIA2 and UALCAN online databases, SNHG3 and NEAT1 were significantly up-regulated in prostate cancer." (PMID 36890836, 2023). "Specifically, ZNFX1 antisense RNA 1 (ZFAS1) and small nucleolar RNA host gene 3 (SNHG3) have been shown to bind miRNAs that inhibit EMT and promote the apoptosis of prostate cancer cells." (PMID 33672595, 2021). "Mechanistically, SNHG3 endogenously absorbs miR-577, thereby positively expressing smad ubiquitin regulatory factor 1 (SMURF1) and promoting the development of prostate cancer." (PMID 33292213, 2020). "On the whole, SNHG3 endogenously sponged miR‐577 to elevate SMURF1 expression, thus facilitating malignant phenotype of prostate cancer." (PMID 32248648, 2020). "In our study, we assessed the expression of SNHG3 in human normal prostate epithelial cells (RWPE1) and prostate cancer cells (PC3, DU145, 22RV1, LNCaP) at the beginning using qRT‐PCR assay." (PMID 32248648, 2020). "Research using the Cancer Genome Atlas Prostate Adenocarcinoma (TCGA-PRAD) database revealed higher SNHG3 expression in prostate cancer patients with bone metastasis (PC/BM) compared to non-metastatic cases (PC/nBM)." (PMID 41042421, 2025). "Furthermore, increased SNHG3 levels correlated with shorter OS (HR = 3.02, 95% CI: 1.16–7.86, p = 0.028) and BMFS (HR = 2.41, 95% CI: 1.03–5.61, p = 0.04) in prostate cancer patients, as demonstrated by in-house tissue samples." (PMID 41042421, 2025). "This study highlights the role of the SNHG3/miR-152-3p/SLC7A11 axis in promoting prostate cancer progression by influencing methionine-dependence, underscoring the significance of miR-152-3p in inhibiting prostate cancer." (PMID 39606232, 2024). "We innovatively uncovered the oncogenic role of SNHG3 and SMURF1 in prostate cancer, which might provide a new insight into identifying the biomarkers for prostate cancer." (PMID 32248648, 2020). "Although SNHG3 (small nucleolar RNA host gene 3) has been investigated in many cancers, now researches on the role and mechanism of SNHG3 in prostate cancer are lacked." (PMID 32248648, 2020). "All the results above explained that SNHG3 accelerated prostate cancer progression by sponging miR‐577 to up‐regulate SMURF1 expression, suggesting that SNHG3 may act as a biomarker for prostate cancer patients." (PMID 32248648, 2020). "We experimentally discovered demonstrated that the carcinogenic effects of SNHG3 and SMURF1 in prostate cancer may provide new ideas for biomarkers of prostate cancer." (PMID 33292213, 2020). "Also, SNHG3 targets miR-577 to up-regulate SMURF1 and heighten the development of prostate cancer." (PMID 35475457, 2022). "However, the role of SNHG3 is still not clear in prostate cancer." (PMID 32248648, 2020).
liver cancer (12 papers, 2019 to 2026). An epithelial or non-epithelial malignant neoplasm that arises from the liver. "Another study has demonstrated that SNHG3 in liver cancer cells can regulate BMI1 through ceRNA mechanism, thereby affecting the malignant behavior of liver cancer." (PMID 36208024, 2023). "and the overexpression of SNHG3 can promote cell invasion and epithelial-mesenchymal transition in liver cancer." (PMID 34991609, 2022). "SNHG3, small nucleolar RNA host gene 3, has been revealed to be oncogenic in multiple human cancers, including colorectal, ovarian, gastric, and liver cancer." (PMID 35030969, 2022). "In our study, the expression of SNHG3 in liver cancer tissues was significantly increased, and it was significantly associated with poor prognosis in patients with liver cancer." (PMID 35431958, 2022). "SNHG3 plays a vital role in the occurrence and development of many tumors, including liver cancer." (PMID 35431958, 2022). "SNHG3 is up-regulated in liver cancer, silencing SNHG3 may impair tumor progression, and miR-139-5p has been proved to bind with SNHG3 to play a regulatory role." (PMID 34324544, 2021). "In vitro colony formation and tumor sphere formation assays showed that SNHG3, SNHG5, SNHG9, and DNACR enhance the stem‐like properties of liver cancer stem cells." (PMID 41474641, 2026). "Furthermore, in vivo experiments demonstrated that knocking down SNHG3, SNHG5, SNHG9, and DNACR inhibits the growth of liver cancer stem cells or reduces the expression of stem cell marker proteins in tumors." (PMID 41474641, 2026). "In HCC cell lines, SNHG3 overexpression promotes the proliferation, migration, and EMT, and inhibits apoptosis, while higher levels of SNHG4 are more likely to indicate poor prognosis in liver cancer." (PMID 35754846, 2022).